COL11A1 (collagen type XI alpha 1 chain)
Diseases named in the same sentence as COL11A1 in open-access papers (continued):
Sharing a sentence is not in itself a finding about the gene and the disease.
triple-negative breast carcinoma (1 paper, 2025). An invasive breast carcinoma which is negative for expression of estrogen receptor (ER), progesterone receptor (PR), and human epidermal growth factor receptor 2 (HER2). "Collagen subunit proteins COL1A1, COL1A2, COL3A1, and COL11A1 have been related to triple-negative breast cancer: COL1A1 expression is elevated in TNBC tissues and is associated with increased tumor stiffness, promoting cancer progression and metastasis, making it an independent prognostic factor." (PMID 40867231, 2025).
cancer (163 papers, 2008 to 2026). A tumor composed of atypical neoplastic, often pleomorphic cells that invade other tissues. "By analyzing multiple scRNA‐seq and spatial transcriptomic datasets, we identified a unique subset of CXCL14+ myofibroblastic CAFs (myCAFs), emerging during the early differentiation phase of pan‐cancer invasiveness‐associated THBS2+ POSTN+ COL11A1+ myCAFs." (PMID 40162549, 2025). "Type XI collagen (COL11A1), a minor fibrillar collagen secreted by cancer-associated fibroblasts, has recently emerged as a stromal biomarker linked to tumor progression, immune modulation, and poor prognosis in several solid malignancies." (PMID 41462920, 2025). "The association between COL11A1 and malignant tumors has only been investigated in a few published articles, including our previous study." (PMID 39845732, 2025). "Mechanistically, COL11A1 is predominantly produced by cancer-associated fibroblasts (CAFs) within the tumor microenvironment." (PMID 41462920, 2025). "ROC analysis further validated the utility of COL11A1 as both a diagnostic and prognostic marker, reinforcing its potential significance in cancer diagnostics and patient prognosis assessment." (PMID 39845732, 2025). "Heat shock protein 27 (HSP27), a downstream effector of COL11A1, is associated with chemotherapy resistance in many types of cancer." (PMID 40514365, 2025). "Overexpression of COL11A1 has been associated with an adverse outcome in a variety of primary cancers, including breast and pancreas." (PMID 39845732, 2025). "Collagen type XI alpha 1 (COL11A1) is a novel biomarker that is associated with chemotherapy resistance in a variety of cancers." (PMID 40514365, 2025). "Further, COL11A1 missense variants have been shown to evoke transcriptional changes in ECM genes in cancer cells." (PMID 38277211, 2024). "Pan-cancer gene-level targets include procollagen 11A1 (COL11A1), which encodes one of the two alpha chains of type XI collagen and is expressed at high prevalence in OS and CPC." (PMID 38702309, 2024). "COL11A1 was previously identified as a specific marker for cancer-associated fibroblasts (CAFs) and primarily overexpressed by a subset of CAFs adjacent to cancer cells or within the tumor." (PMID 38806505, 2024). "The largest group of TAAs (n = 14) derived from genes reported as markers of cancer-associated fibroblasts (CAFs) (COL11A1, COL10A1, LRRC15)." (PMID 37906288, 2024). "Our studies demonstrated that FN1 and COL11A1, targets that are associated with the matrisome, are expressed by cancer cells." (PMID 38702309, 2024). "Type XI alpha 1 collagen (COL11A1) is a protein specifically expressed by fibroblasts associated with different types of malignant tumors (breast, pancreas, colon, lung, ovary, etc.), as evidenced by studies on tissues both at the RNA and protein levels." (PMID 36834987, 2023). "High expression of minor fibrillar collagen COL11A1 has been associated with disease progression and poor survival in ovarian and other cancers." (PMID 37509222, 2023). "In other studies, COL11A1 expression has been almost exclusively localized to cancer-associated stromal cells." (PMID 37509222, 2023). "COL11A1 is associated with poor clinical outcomes in numerous solid cancers and is a novel biomarker and a pivotal target in cancer." (PMID 37006317, 2023). "COL11A1 encodes a collagen protein mainly expressed in the cartilage, which has been associated with bone disorders and cancers." (PMID 36400229, 2023). "COL11A1 is reported to be increased in several cancers and high levels of COL11A1 are often associated with poor survival, chemotherapy resistance and recurrence." (PMID 37051524, 2023). "High levels of COL11A1 usually predict poor prognosis, owing to its association with angiogenesis, invasion, and drug resistance in cancer." (PMID 35847935, 2022).
cancer (continued). "To address this possibility, we first detected the function of COL11A1 in the expression of cancer stem cell (CSC)-associated markers (cluster of differentiation (CD)-24 and CD44) in PDAC using Western blotting." (PMID 35327583, 2022). "Several studies have revealed that a stromal expression of COL11A1 is implicated in the malignant transition in these cancer types." (PMID 34378164, 2022). "COL11A1 encodes a chain of type XI collagen, which locates in the extracellular matrix, and is up-regulated in various cancers." (PMID 35281069, 2022). "Recent studies have shown that COL11A1 is associated with the occurrence and development of many kinds of malignant tumors." (PMID 36160004, 2022). "High-level expression of COL11A1 is related to mesenchyme-derived tumors, cancer-associated stromal cells, and carcinoma progression." (PMID 36415513, 2022). "Procollagen 11A1 (COL11A1) is a central component of the extracellular matrix in many carcinomas, which is considered to be mainly produced by cancer associated fibroblasts (CAFs)." (PMID 34378164, 2022). "In each of the 33 cancer types, we ranked all protein-coding genes in terms of the association (using the metric of mutual information) of their expression with that of gene COL11A1." (PMID 34283835, 2021). "In summary, the expression of COL11A1 is elevated in several cancers and is associated with poor survival, chemoresistance, and recurrence." (PMID 33668097, 2021). "Top 15 ranked genes in terms of fold change (FC) for three different cancer types revealing the signature of the COL11A1-expressing cancer-associated fibroblasts." (PMID 34283835, 2021). "Given that COL11A1 expression is specific to cancer-associated stromal cells, targeting COL11A1 will significantly enhance the therapeutic specificity and reduce the risk of off-target effects." (PMID 33668097, 2021). "In each of the remaining 22 cancer types, we then ranked all long noncoding RNAs (lncRNAs) and microRNAs (miRNAs) in terms of their association with COL11A1." (PMID 34283835, 2021). "We also assessed the top genes differently expressed between penta- and tetra-cultures, where we identified several ECM molecules previously associated with poor prognosis in cancer (COL11A1, TNC, TGFβ1)." (PMID 34189439, 2021). "COL11A1 point mutation therefore induces a gene set associated with overall worse cancer survival that is enriched for links to integrin signaling." (PMID 34584216, 2021). "Our results indicate that the cancer invasiveness-associated COL11A1-expressing CAFs are produced as a result of the interaction of tumor cells with the adipose microenvironment." (PMID 34283835, 2021). "Despite significant advancement of our knowledge on the biological functions of COL11A1 in cancer progression and the underlying mechanisms, there are still many questions to be addressed." (PMID 33668097, 2021). "When compared to respective normal tissues, the authors demonstrate elevated levels of COL11A1 expression in tumor endothelial cells, which is associated with poor outcomes in different cancer types." (PMID 33668097, 2021). "In solid tumors, although a small number of cancer cells overexpress COL11A1, COL11A1 is predominantly overexpressed by a subset of cancer-associated fibroblasts (CAFs) adjacent to cancer cells, suggesting COL11A1 as a specific marker for CAFs." (PMID 33668097, 2021). "COL11A1 is predominantly expressed and secreted by a subset of cancer-associated fibroblasts, modulating tumor-stroma interaction and mechanical properties of extracellular matrix." (PMID 33668097, 2021). "Here we show that COL11A1 is recurrently mutated in cSCC and that its cancer-associated mutation boosts neoplastic invasion in tissue." (PMID 34584216, 2021). "It has been concluded that COL11A1 expression is a biomarker of human carcinoma‐associated stromal cells and carcinoma progression." (PMID 33932142, 2021).
cancer (continued). "COL11A1 has been reported to be secreted by cancer associated fibroblasts and is closely correlated with the progression of multiple cancer types." (PMID 30410422, 2018). "Recent reports have established an association between Col11a1 expression and cancer, a process that encompasses many parallels with wound healing (Schäfer and Werner, 2008)." (PMID 28331057, 2017). "In this study, the molecular mechanisms underlying COL11A1-increased cancer drug resistance were elucidated, providing an understanding of the mode of action." (PMID 26087191, 2015). "Though COL11A1 is clearly associated with cancer progression and metastasis, there are a limited number of studies detailing the role and mechanism of COL11A1 overexpression in metastasis." (PMID 26579497, 2015). "Some cancer-associated stromal cells seem to be derived from bone marrow mesenchymal cells; the expression of the COL11A1 gene and the parallel immunodetection of procollagen 11A1 have not been evaluated in these latter cells, either." (PMID 25417197, 2014). "Secreted primarily by cancer-associated fibroblasts (CAFs), COL11A1 may serve as a novel stromal biomarker and a potential therapeutic target within the tumor microenvironment." (PMID 41462920, 2025). "COL11A1 has been implicated in various conditions beyond cancer, including fibrotic disorders, where it may exert similar or distinct effects." (PMID 40322427, 2025). "Importantly, emerging evidence indicates that COL11A1 is associated with cancer progression that can promote tumor growth, migration, invasion, metastasis, and chemotherapy resistance." (PMID 38649961, 2024). "Their differentiation into COL11A1+ CAFs, accompanying the transition to metastasis, may underlie a mechanism that accounts for the role of adipose tissue in cancer aggressiveness." (PMID 38466528, 2024). "In addition, upregulation of COL11A1 is associated with cancer recurrence and poor survival and in some types of cancer, such as breast, colorectal, gastric, and so on." (PMID 38649961, 2024). "Moreover, COL11A1 can serve as a specific biomarker for cancer-associated fibroblasts (CAFs) and as a novel therapeutic target for cancer treatment." (PMID 37386587, 2023). "COL11A1 is associated with poor prognosis in several cancer types, and may have potential as a prognostic biomarker in pancreatic cancer." (PMID 37188691, 2023). "In addition, upregulation of COL11A1 is associated with cancer recurrence and poor survival and serves as a diagnostic indicator." (PMID 35892083, 2022). "Existing studies have shown that abnormal upregulation of COL11A1 may be associated with multiple tumor types, which was also confirmed by the pan-cancer analysis in this study." (PMID 36160004, 2022). "Therefore, COL11A1 can be used as a risk factor for a variety of human malignant tumors and a marker for predicting poor prognosis." (PMID 36160004, 2022). "After assessment for background mutation rate differences in each tumor type, analysis of cancer sequencing data from TCGA found COL11A1 commonly mutated across multiple epithelial malignancies, including cancers of the lung, esophagus, stomach, cervix, and colon." (PMID 34584216, 2021). "Correlation between ITGA11 and COL11A1 expression levels in cancer‐associated fibroblasts." (PMID 33682233, 2021). "In addition, overexpressed ITGA11 accompanied by COL11A1 expression in cancer stroma was associated with a poor clinical outcome." (PMID 33682233, 2021). "In this context, higher expression of COL11A1 protein has been reported in the cancerous tissue and has been found to be linked with poor progression-free and overall survival across the various types of cancers." (PMID 33597969, 2021). "Interestingly, COL11A1 expression is increased in several cancers and high levels of COL11A1 are often associated with poor survival, chemoresistance, and recurrence." (PMID 33668097, 2021).
cancer (continued). "The association of COL11A1 overexpression with decreased cancer survival spans a diverse array of neoplasms, including head and neck, breast, ovarian, colon, and lung, suggesting a potentially broad role for COL11A1 in a wide spectrum of cancers." (PMID 34584216, 2021). "Indeed, dipeptidyl peptidase 4 (DPP4), fibroblast activated protein (FAP), and collagen type XI (COL11A1), markers of activated/cancer-associated fibroblasts, are expressed at very low levels." (PMID 33413690, 2021). "Interestingly, Ingenuity pathway analysis of these COL11A1-correlated genes placed TGFβ1 as a master regulator of the pan-cancer COL11A1-correlated genes and COL11A1-associated biological functions." (PMID 33668097, 2021). "Elevated COL11A1 expression in HNSCCs and CAFs has been reported to enhance tumour cell proliferation, migration and invasion and elevated levels of COL11A1 are associated with the progression of carcinomas of different types." (PMID 31717573, 2019). "This remarkable consistent strong association of COL11A1 with the staging phenotype (specific to each cancer type) suggests that it could be used as a "proxy" of the MAF signature." (PMID 21047417, 2010). "In addition, COL11A1 can serve as a specific marker for cancer-associated fibroblasts (CAFs)." (PMID 34944877, 2021). "COL11A1, (collagen, type XI, alpha 1), is essential for normal formation of cartilage collagen fibrils and the cohesive properties of cartilage and has been identified as a potential metastasis-associated gene in lung, oral cavity, and in cancer associated fibroblasts." (PMID 27876019, 2016). "Thus, the in vivo up-regulation of the COL11A1 gene may be considered as a biomarker of cancer-associated stromal cells." (PMID 25417197, 2014). "DDR2-COL11A1 exhibited the most dramatic coupling intensification, increasing from R2=0.007 in normal tissue to R2=0.549 in carcinoma, accompanied by 1.99-fold COL11A1 upregulation." (PMID 41828724, 2026). "COL11A1 is a recognized cancer-specific fibroblast marker that can promote tumor progression by influencing ECM remodeling and anti-tumor immune responses." (PMID 40940956, 2025). "COL11A1 is a fibrillar collagen protein, primarily involved in cartilage formation, which is thought to be a novel biomarker with specificity to CAFs and cancer progression, through ECM remodeling." (PMID 41450913, 2025). "We identified a population of cancer-associated fibroblasts (CAFs), marked by the expression of genes such as COL1A1, COL3A1, COL11A1, and ACTA2, which are known to contribute to the activation of EMT programing." (PMID 40950184, 2025). "COL11A1 upregulation is associated with TGF-β1, Wnt, and Hh signaling pathways, which are especially active in cancer-associated stromal cells, including CAFs." (PMID 39926258, 2025). "Conversely, within lymph node metastasis tissues, we observed a significant decrease in COL11A1 mRNA levels compared to their matched primary carcinoma tissues (n = 30, p=0.005)." (PMID 39845732, 2025). "And more importantly, overexpression of COL11A1 closely correlated with poor prognosis in human malignant tumors." (PMID 38806505, 2024). "This multifaceted role of COL11A1 in both normal physiological processes and pathologies like cancer and connective tissue disorders highlights its significance in cellular and molecular biology." (PMID 38392197, 2024). "On the other hand, the additional 5 genes showed a high R-index = 0.9 or beyond, and COL11A1 and TAGLN expressions as shown in red letters were uniquely associated with SPARC expression in cancer stroma of the TNBC tumors (both R-index below 0.6 in total BC)." (PMID 39335478, 2024). "To further understand the expression of COL11A1 in cancers, we also evaluated COL11A1 expression in TCGA pan-cancer dataset." (PMID 38649961, 2024).
cancer (continued). "A variety of reports have demonstrated a remarkable increase in the expression of COL11A1 in various cancer types, such as pancreatic, ovarian, lung, esophageal, colorectal, gastric and breast cancers." (PMID 38806505, 2024). "We investigated the association between COL11A1 expression and ICP genes in human cancers to explore the potential function of COL11A1 in immunotherapy." (PMID 38649961, 2024). "Patients with high COL11A1 correlated with decreased survival was consistent with the notion that it is a prognostic biomarker for various cancers including NSCLC." (PMID 39478862, 2024). "KRT19, CEA, COL1A2, and COL11A1 expression levels were much higher in cancer patients (KRT19 = 66.04 ± 14.29-fold; CEA = 245.81 ± 84.63-fold; COL11A1 = 47.80 ± 7.51-fold; COL1A2 = 40.64 ± 6.00-fold)." (PMID 36834987, 2023). "The 5 members of the M0-ECM signature, FN1, VCAN, COL11A1, SFRP2, and MXRA5, have been associated with cancer progression, through markers of prognosis or the process of metastasis." (PMID 37188691, 2023). "Some other studies reported that COL11A1 was also involved in the CAF-cancer cell interaction and promote tumor progression through different mechanisms." (PMID 36744260, 2023). "We further investigated the minor fibrillar collagen, collagen XI alpha 1 (COL11A1), and found that COL11A1 expression originates specifically from cancer cells and is strongly correlated with both Wnt/β-catenin activation and poor patient survival." (PMID 37509222, 2023). "In contrast, ACC is one of the most stroma-poor cancer types in the TCGA cohort, and we found that COL11A1 expression is present in both NCI-H295R cells and in the neoplastic cells present in human ACC samples." (PMID 37509222, 2023). "COL11A1 expression is upregulated in several cancer types, including ovarian, breast, pancreatic, non-small-cell lung, and colorectal cancer." (PMID 37386587, 2023). "Another CC term, extracellular matrix (associated with the HubGs COL11A1 and COL10A1), is involved in the development and progression of cancer and is effective for cancer therapy." (PMID 37893423, 2023). "Collagen type X1 alpha 1 (COL11A1), from the collagen family, is mostly expressed and released by cancer-related fibroblast subsets, and modulates matrix-tumor interaction and the mechanical characteristics of ECM." (PMID 36843929, 2023). "COL11A1 can also promotes cancer cell migration, metastasis, and therapy resistance by activating multiple signaling pathways." (PMID 37207166, 2023). "COL11A1 is an isoform of fibrillar collagen that is involved in the proliferation, migration and apoptosis of cancer cells." (PMID 36999888, 2023). "It was described in a meta-analysis that overexpression of COL11A1 (measured using mRNA) is a differential event between high- and low-grade tumors in different carcinoma phenotypes." (PMID 37760937, 2023). "Afterward, it was discovered by Transwell and wound healing assays that the invasive and migratory functions of cancer cells were remarkably elevated after overexpressing COL11A1." (PMID 35669376, 2022). "The results showed that the levels of mRNA transcription and protein expression of COL11A1 in cancer tissues were significantly up-regulated compared with those in adjacent tissues." (PMID 36160004, 2022). "Cancer-associated-fibroblasts (CAFs), the core functional components of the TME, promotes the EMT process by secreting large amounts of COL11A1 collagen." (PMID 36266702, 2022). "Colony formation assay also displayed that COL11A1 overexpression remarkably elevated colony formative ability of cancer cells, while simultaneously overexpressing COL11A1 as well as miR-339-5p greatly reduced the ability." (PMID 35669376, 2022). "Inhibition of TGF-β, a growth factor known to induce COL11A1 expression, has been explored as an anti-cancer therapy in the clinic." (PMID 35847935, 2022).